TGFB1 (transforming growth factor beta 1)
Diseases named in the same sentence as TGFB1 in open-access papers (continued):
Sharing a sentence is not in itself a finding about the gene and the disease.
goiter (3 papers, 2021 to 2024). Enlargement of the thyroid gland usually caused by lack of iodine in the diet, hyperthyroidism, or thyroid nodules. "TGFB1 mRNA expression was upregulated in PTC and downregulated in benign samples, differentiating malignant from benign nodules (p<0.0001); PTC from goiter (p<0.0001); and PTC from FA (p<0.0001)." (PMID 33905626, 2021).
HELLP syndrome (3 papers, 2022 to 2025). A life-threatening condition that can potentially complicate pregnancy. "sEng, which is believed to work as an anti-angiogenic protein by impairing the binding of transforming growth factor beta-1 to its receptors, is most frequently increased among women with severe PreE and HELLP syndrome." (PMID 35200304, 2022). "The expression of IGFBP-3 is elevated in HELLP syndrome, which may subsequently promote cell apoptosis by affecting the expression and function of IGF-1, VEGF, and TGFβ1 in the IGF/PI3K/Akt, TGF-β1/Smad3, and VEGF/eNOS/NO pathways." (PMID 37950229, 2023).
hypercoagulability (3 papers, 2022 to 2023). "Among the direct neighbors of TGFB1 and F12 genes within the disease-specific subnetwork, we find disease-specific variants that are related to thrombophilia." (PMID 37098010, 2023). "Moreover, the disease-specific subnetwork contains two thrombophilia-related genes present in the DisGeNet database, TGFB1 (transforming growth factor beta-1, TGFβ-1) and F12 (coagulation factor XII), which are both disease-specific variants." (PMID 37098010, 2023).
hyperostosis (3 papers, 2021 to 2022). Excessive thickening of bone. "The pathogenesis is related to activating mutations in transforming growth factor beta 1, which results in bilateral, symmetric hyperostosis affecting primarily the diaphysis of long bones." (PMID 33937459, 2021).
hyperphosphatemia (3 papers, 2020 to 2024). Abnormally high level of phosphate in the blood. "Moreover, TGFβ1 contributes to the development of medial vascular calcification during hyperphosphatemia, a pathological process promoted by osteo-/chondrogenic transdifferentiation of vascular smooth muscle cells." (PMID 39416879, 2024).
intestinal inflammation (3 papers, 2020 to 2025). "Defective TGFB1 signalling was reported in men under inflammatory conditions of IBD and in chickens challenged with Salmonella Enteritidis, while restoration of TGFB1 signalling has shown therapeutic potential in experimental intestinal inflammation models in mice." (PMID 40275387, 2025).
Lipedema (3 papers, 2020 to 2025). Disorder of adipose tissue characterized by symmetric and bilateral enlargement of the lower extremities due to abnormal deposition of subcutaneous fat often in obese women. "For instance, the cytokines VEGFA, TGFα and TGFβ1 were among the inflammatory markers upregulated in lipedema." (PMID 36387874, 2022).
mastocytosis (3 papers, 2017 to 2022). A clonal myeloproliferative neoplasm characterized by the proliferation and accumulation of neoplastic mast cells in one or multiple organs or organ systems. "Utilising this workflow, we identified and validated CXCL7, LBP, TGFβ1 and PDGF receptor-β as novel biomarkers for systemic mastocytosis." (PMID 35332176, 2022).
measles (3 papers, 2021 to 2023). A highly contagious viral infection caused by the measles virus. "T helper (Th) cells expressing IL21 (1–10%), TGFB1 (2.9–9.5%), and IL21 plus TGFB1 (0.3–3.5%) were as frequent among the SARS-CoV-2-reactive Th cells as among measles-reactive Th cells of a healthy control (2%, 6%, 0.6%)." (PMID 33785765, 2021).
mental disorder (3 papers, 2020 to 2022). A disease that has its basis in the disruption of mental process. "For Mental Disorders, the path with the strongest literature backing (i.e., total number of publications) was the one linking TGFB1 with this disease group via IL-6, both genes co-expressed in the cerebral cortex." (PMID 35360842, 2022). "Moreover, there are 22 different one-hop paths (TGFB1—gene X—Mental Disorders) and 926 different two-hops paths (TGFB1—gene Y—gene Z—Mental Disorders) between TGFB1 and Mental Disorders in which all genes are expressed in the cerebral cortex." (PMID 35360842, 2022). "Although TGFB1 is considered to play important role in psychoneuroimmunology, there is only few research about its association with mental disorders, and interestingly there is no other studies investigated role of mentioned rs1800469 in MDD." (PMID 32140313, 2020).
neurofibromatosis (3 papers, 2018 to 2024). A hereditary neoplastic syndrome in which tumors grow in the nervous system. "TGFβ-1-induced EMT was associated with a 4-fold increase in Panc-1 cell invasiveness, which further increased ~10-fold upon knockdown of the tumor suppressor Merlin (Neurofibromatosis type 2)." (PMID 32457840, 2020).
neutropenia (3 papers, 2022 to 2024). A decrease in the number of neutrophils found in the blood. "Finally, the observed mixed (decreased and increased) probability of neutropenia in carriers with 1 or 2 copies of WT alleles of TGFB1 limits meaningful discussion of a possible association." (PMID 37162533, 2023).
orofacial cleft (3 papers, 2019 to 2021). A disorder of facial skeleton that is characterized by cleft lip and/or cleft palate that result in feeding, speech and hearing problems caused by failures during development. "To show that TGFβ1 increase can affect downstream genes associated with orofacial clefts, we looked at expression of SOX9 transcription factor." (PMID 33577554, 2021). "TGFβ1 showed the highest number of connections to known genes associated with orofacial clefts." (PMID 33577554, 2021). "Two of these possible factors, which could possibly play a role in the development of orofacial clefts, are transforming growth factor beta 1 (TGF-β1) and epidermal growth factor receptor (EGFR)." (PMID 34393631, 2021).
ovarian adenocarcinoma (3 papers, 2016 to 2023). An adenocarcinoma that arises from the ovary. "The study aims to profile the dual-specificity phosphatases (DUSP) expression in response to Transforming growth factor β1 (TGFβ1)-induced epithelial-mesenchymal transition (EMT) in ovarian adenocarcinoma cells." (PMID 37476896, 2023). "The ovarian adenocarcinoma cell line SKOV3 was used as a TGFβ1-induced EMT model." (PMID 37476896, 2023).
Ovarian cyst (3 papers, 2019 to 2025). The presence of one or more cysts of the ovary. "In the mouse model, in vitro fertilization of the egg obtained by injecting TGFβ1 into mouse ovarian cysts inhibits oocyte development, possibly because TGFβ1 induces the premature differentiation and proliferation of granulosa cells." (PMID 35741771, 2022).
ovarian hyperstimulation syndrome (3 papers, 2020 to 2024). A complication of ovulation induction in infertility treatment. "TGFβ1 and TGFβ3, but not TGFβ2, are upregulated in the ovaries of ovarian hyperstimulation syndrome." (PMID 38791596, 2024).
Peptic ulcer (3 papers, 2015 to 2025). The term peptic ulcer refers to acid peptic injury of the digestive tract, resulting in mucosal break reaching the submucosa. "BXD modulates the TGF-β/Smad signaling pathway by suppressing transforming growth factor-beta 1 (TGF-β1) and Smad3 expression while upregulating Smad7 in peptic ulcer patients." (PMID 40102869, 2025).
thyroid nodule (3 papers, 2014 to 2024). A small circumscribed mass in the THYROID GLAND that can be of neoplastic growth or non-neoplastic abnormality. "Furthermore, TGFB1 rs1800472 was previously associated with decreased risk to thyroid nodules." (PMID 33905626, 2021). "First, in this study, we aimed to investigate the role of TGFB1, TGFBR1, and TGFBR2 SNPs in the susceptibility to thyroid nodules malignancy and their correlation to clinical and anatomopathological characteristics." (PMID 33905626, 2021). "Next, based on in silico analysis of the possible impact of a nonsynonymous SNP (nsSNP), we investigated mRNA expression of TGFB1 and its receptors in a well-characterized group of thyroid nodule patients carefully followed-up by a same group of health-care providers for a relatively long time." (PMID 33905626, 2021). "Our data suggest TGFB1 mRNA expression can help rule out malignancy in thyroid nodules with a NPV of 98% and deserves to be tested in FNA samples." (PMID 33905626, 2021). "Evaluation of TGFB1 and TGFBR1 mRNA levels may be useful to identify malignancy in thyroid nodules." (PMID 33905626, 2021). "In addition, evaluating TGFB1 and TGFBR1 mRNA levels may be useful to characterize thyroid nodules malignancy." (PMID 33905626, 2021).
acromegaly (2 papers, 2020 to 2022). Acromegaly is an acquired disorder related to excessive production of growth hormone (GH) and characterized by progressive somatic disfigurement (mainly involving the face and extremities) and systemic manifestations. "Differences between transcriptomic groups were also observed in expression levels of proliferation-related genes CCND1, CDKN1B, and MKI67 and genes involved in cell signaling TGFB1 and STAT3 that all have a reported role in acromegaly patients’ outcome." (PMID 36497102, 2022).
adhesive capsulitis (2 papers, 2016 to 2023). "In the present study, we quantified the mRNA expression of the TGFβ1, TGFβR1, LOX, PLOD1, PLOD2, COMP, FN1, TNC and TNXB genes in glenohumeral synovium/capsule samples collected from patients with adhesive capsulitis and from controls." (PMID 27438566, 2016).
AIDS dementia complex (2 papers, 2019 to 2025). A neurologic condition associated with the ACQUIRED IMMUNODEFICIENCY SYNDROME and characterized by impaired concentration and memory, slowness of hand movements, ATAXIA, incontinence, apathy, and gait difficulties associated with HIV-1 viral infection of the central nervous system. "TGFβ-1 is rapidly produced when neuronal injury occurs and has been detected in brain lesions in the astrocytes of HIV encephalitis patients." (PMID 31829243, 2019).
chorioamnionitis (2 papers, 2005 to 2023). A morphologic finding indicating inflammation of the fetal sac membranes. "In preterm women without histologic chorioamnionitis frequencies for the IL10-1082A/-819T/-592A (ATA) haplotype, MBL2 codon 54Asp (the MBL 'B' allele), TNFRSF6-1377A/-670G (AG) haplotype and TGFB1-800G/-509T (GT) homozygosity were similar to reported Caucasian controls." (PMID 15723707, 2005).
congenital cataracts (2 papers, 2011 to 2021). "At present, it is difficult to determine whether systemic TGFβ1 and TGFβ2 overexpression in congenital cataracts might act as a causative or concomitant factor." (PMID 22128246, 2011). "In the PBMCs of patients with congenital cataracts, the expression of TGFβ3 (Me=9395) was the highest and significantly greater than those of TGFβ1 (Me=4475, p=0.015, post hoc test) and TGFβ2 (Me=343, p<0.001)." (PMID 22128246, 2011). "A comparative analysis of all TGFβ mRNA copies/μg of total RNA revealed that TGFβ1 was a predominant isoform in the ALCs of patients with congenital cataracts." (PMID 22128246, 2011). "In our research, the upregulation of TGFβ1 and TGFβ2 gene expression in the PBMCs of patients with congenital cataracts might suggest that the processes occurring in the lens are affected by systemic expression levels of these cytokines, especially during fetal life when the lens is vascularized." (PMID 22128246, 2011).
Dyskinesia (2 papers, 2022 to 2024). A movement disorder which consists of effects including diminished voluntary movements and the presence of involuntary movements. "Transcriptional network and upstream regulatory factor analysis indicated that TGFβ1 pathway was essential to the pathogenic mechanism of long-term L-Dopa therapy caused dyskinesia in PD patients." (PMID 34967706, 2022). "It was reported that TGFβ1 and TGFβ2 levels were increased in ventricular cerebrospinal fluid of PD, while upregulation of TGFβ1 was associated with dyskinesia caused by long-term L-dopa therapy." (PMID 34967706, 2022).
Follicular Cyst (2 papers, 2020 to 2023). Cyst due to the occlusion of the duct of a follicle or small gland. "FGF7 regulated the PPAR signaling pathway (FABP5 and SCD) and the MAPK signaling pathway (FGF1, FGFR2, IL1A, TGFB1, and CSF1) and pathways in cancer (IL7, CD44, SMAD2, and MMP2) may be involved in the formation of follicular cysts." (PMID 38274662, 2023).
hepatocellular adenoma (2 papers, 2011 to 2020). A benign epithelial neoplasm arising from the hepatocytes. "Depending on the intensity of TGFβ1 induction, the fish developed different lesions in the liver; low and moderate levels of TGFβ1 caused hyperplasia and hepatocellular adenoma and high levels of TGFβ1 caused HCC to develop." (PMID 34766114, 2020).
hyperparathyroidism (2 papers, 2022 to 2025). Hyperfunction of the parathyroid glands resulting in the overproduction of parathyroid hormone. "Hyperexpression of miR-24 inhibits production of parathyroid hormone by binding CDKN1B/p27, CDKN2A/p16, TGFβ1, and CASP8 transcripts, which are involved in the development of hyperparathyroidism." (PMID 40217882, 2025).
idiopathic scoliosis (2 papers, 2016 to 2018). A scoliosis with no known cause. "On the basis of the present results, TGFB1 (-509C/T) can be considered as a predisposing factor of idiopathic scoliosis with a moderate individual effect on deformity development in Bulgarian patients." (PMID 30079294, 2018). "Additional larger replication studies are necessary to confirm the relationship between the TGFB1 locus and certain subtypes of IS in specific population groups and to detect a potential association between the TGFB1 gene and idiopathic scoliosis in male patients." (PMID 30079294, 2018).
leukopenia (2 papers, 2022 to 2025). "Building upon the multilayer module network constructed, we identified key targets of CB herbs in the treatment of leukopenia, including TGFB1, C1R, CD4, and HMGB1, which regulate leukopenia through signal transduction, cellular process, and immune response." (PMID 40890790, 2025).
lymphocytic leukemia (2 papers, 2021 to 2023). "We found that TGFB1 was positively correlated with most of the immunomodulatory factors in myeloid and lymphoid leukemias as well as DLBCL but negatively correlated with most in MM." (PMID 37925591, 2023). "Myeloid malignancies like AML, MDS, and CML generally showed higher TGFB1 expression when compared to normal samples and the opposite was seen in lymphoid leukemias (ALL and CLL)." (PMID 37925591, 2023).
macular edema (2 papers, 2013 to 2020). "Furthermore, in DR management it would be useful to monitor not only the macular edema and retinal fundus, but also clinical laboratory parameters such as HbA1c, and possibly TGFβ1 serum levels." (PMID 33334029, 2020).
Osteochondrosis (2 papers, 2019 to 2025). Abnormal growth ossification centers in children. "The TGFβ1 gene, known to be deficient in chondrocytes at sites of osteochondrosis, stimulates their proliferation." (PMID 41465565, 2025). "When osteochondrosis scores were used for association analysis, the metalloproteinase 3 (MMP3) involved in extracellular matrix degradation in joints and transforming growth factor beta 1 (TGFβ1) appeared to have an effect on this leg-weakness-related trait." (PMID 41465565, 2025).
pelvic organ prolapse (2 papers, 2025). Abnormal descent of a pelvic organ resulting in the protrusion of the organ beyond its normal anatomical confines. "The aim of this study is to investigate the mechanism of action and correlation between transforming growth factor beta 1 (TGF-β1) and β-catenin in pelvic organ prolapse (POP)." (PMID 40129469, 2025).
placental diseases (2 papers, 2020 to 2022). "The TGFβ1/SMAD2/3-SMAD4 cascade can even upregulate cyclooxygenase-2 (COX-2), which in turn suppresses HTR8/SVneo TB cell invasion, suggesting TGFβ1/COX-2 as useful targets to treat placental disorders." (PMID 32183218, 2020).
pneumococcal pneumonia (2 papers, 2012). A febrile disease caused by STREPTOCOCCUS PNEUMONIAE. "qRT-PCR analysis was performed on lung tissue from intranasally-infected BALB/c and CBA/Ca mice to determine Tgfb1 expression over the course of pneumococcal pneumonia." (PMID 22563306, 2012). "The Tgfb1 gene is located within this region of chromosome 7 and this prompted us to investigate the contribution of TGF-β and its downstream targets – including T regulatory cells - to the differing susceptibilities of BALB/c and CBA/Ca mice to invasive pneumococcal pneumonia." (PMID 22563306, 2012).
Primary glaucoma (2 papers, 2015 to 2021). "In the current analysis, association of -509C > T promoter variant in TGFB1 with primary glaucoma was assessed." (PMID 33832461, 2021). "Therefore, in the present study, association of the TGFB-1 -509C > T promoter polymorphism (rs1800469) with primary glaucoma (POAG/PACG) was investigated in a North Indian Punjabi cohort." (PMID 33832461, 2021).
rhinosinusitis (2 papers, 2015 to 2023). "Therefore, in the present study, we induced normal human RECs with TGFβ1 to mimic the EMT conditions that occur during rhinosinusitis." (PMID 36835384, 2023).
schwannoma (2 papers, 2013 to 2025). A benign, usually encapsulated slow growing tumor composed of Schwann cells. "Moreover, TGFβ1, TGFβR1 and TGFβR2 were upregulated in schwannomas, in contrast with previous reports, where no evident changes were observed." (PMID 23354516, 2013).
Varicose veins (2 papers, 2018 to 2021). Enlarged and tortuous veins. "Several other investigators have observed a higher TGFβ1 expression in varicose veins." (PMID 34944071, 2021).
Vestibular schwannoma (2 papers, 2012 to 2024). A vestibular schwannoma (also known as acoustic neuroma, acoustic neurinoma, or acoustic neurilemoma) is a benign, usually slow-growing tumor that develops from the VIIIth cranial nerve supplying the inner ear. "In addition to CCL2, the examination of our cell culture supernatants of VS primary cultures suggests that vestibular schwannoma cells produce the cytokines CCL5, CCL18, TGFB1, and GDF15, which has not yet been investigated for VSs." (PMID 39272860, 2024).
adolescent idiopathic scoliosis (1 paper, 2016). A scoliosis with no known cause arising in adolescent. "The transforming growth factor beta-1 (TGFB1) gene was recently reported to be a new susceptible gene of adolescent idiopathic scoliosis (AIS) in Russian population." (PMID 26758901, 2016).
asbestosis (1 paper, 2025). A lung disorder caused by inhalation of asbestos fibers. "Lung macrophages isolated from humans with asbestosis showed a significant induction in TGFB1, IL10, ARG1, and MRC1 gene expression compared with healthy humans." (PMID 40208691, 2025).
Asperger's syndrome (1 paper, 2018). "For example, plasma TGFβ1 was significantly reduced in adult males with Asperger's syndrome and in children with ASD." (PMID 30483058, 2018).
Bowen disease (1 paper, 2021). "Among the CAFs, we selected T165A from a patient with Bowen disease and T205A from a patient with invasive SCC, based on their high levels of secretion of TGFβ1 and the consistent pattern of expression of the rest of the markers." (PMID 34830768, 2021).
Bruck syndrome (1 paper, 2025). Bruck syndrome is characterized by the association of osteogenesis imperfecta and congenital joint contractures. "Three patients were identified with mutations in the P3H1, LEPRE, CRTAP, SERPINF1, PLOD2 (Bruck syndrome), TGFB1, and SGMS2 genes (Calvarial Doughnut Lesions with Bone Fragility)." (PMID 39941180, 2025).
cervical disease (1 paper, 2022). "TGFB1 variants could contribute to the comprehension of the TGFB1 role in HPV-caused cervical disease." (PMID 36611878, 2022).
cholangitis (1 paper, 2021). An acute or chronic inflammatory process affecting the biliary tract. "Therefore, we investigated whether this pathway is involved in progressive fibrosis after cholangitis by analyzing the expression of IL33, IL13, TGFB1, and COL1A1." (PMID 34858903, 2021).